MYCN (MYCN proto-oncogene, bHLH transcription factor)
Diseases named in the same sentence as MYCN in open-access papers (continued):
Sharing a sentence is not in itself a finding about the gene and the disease.
cancer (continued). "Notably, inhibitors such as the BET protein inhibitor GSK525762, the AURKA inhibitor MLN8237, and the ODC inhibitor DFMO are currently undergoing clinical evaluation for MYCN-driven cancers." (PMID 40027135, 2025). "Given our findings that PA2G4 and c-MYC form a positive forward feedback expression loop in MYC- and MYCN-driven cancers, we hypothesized that WS6 would repress the expression of both proteins in c-MYC-driven malignant cells." (PMID 41002386, 2025). "Targeting activated MYCN has become a focus across childhood and adult cancer." (PMID 39740515, 2025). "Finally, we describe potential therapeutic approaches targeting both MYCN and MDM2 for the treatment of MYCN-driven cancer." (PMID 39802403, 2025). "The oncogene MYCN is well known as having a wide range of cellular targets and has been shown to play a critical role in reshaping cellular metabolism in the context of cancer." (PMID 40993267, 2025). "Additionally, there is growing concern about the role of MYCN in metabolic reprogramming in cancer cells." (PMID 40027135, 2025). "In the context of cancer growth, the functional interplay between MYCN and DDX3X remains enigmatic." (PMID 37975412, 2024). "Such an approach represents a therapeutic approach for MYCN‐driven cancers." (PMID 37975412, 2024). "Moreover, our study along with others are beginning to reveal that proto-oncogenes such as MYC and MYCN can regulate the methylation of splicing factors that provide cancer cells with a mechanism which promotes cell survival." (PMID 38049564, 2024). "The C5/proliferative subtype showed the highest MYCN expression of all cancer types in TCGA." (PMID 38748789, 2024). "In addition, MYCN plays a critical role in cancer onset, progression and invasive tendency, making it a key factor in the maintenance of tumourigenic states in various types of cancer." (PMID 39334719, 2024). "MYCN forms a dynamic complex system with different cofactors on different genomic loci to control the chromatin landscape, guide the expression of genes, and determine the cancer cell identity." (PMID 38547242, 2024). "Recent studies showed that T-UCRs contribute to various cellular pathways, such as DNA damage response, proliferation, chemotherapy response, MYCN (v-myc myelocytomatosis viral related oncogene) amplification, gene copy number and immune response and survival rates in some types of cancers." (PMID 39320855, 2024). "In this study, through protein–protein interactions of 167 protein-coding RNAs of RAB27A overexpressing cells that are likely to be involved in cancer metastatic potential, we identified MYCN as one of the most significant hubs that interact with various other genes." (PMID 38685086, 2024). "Sectioning of the dissected tumors at 27 wpf revealed differences in tissue architecture, where the MYCN-TT–derived tumors comprised large amounts of connective tissue and contained smaller foci of cancer cells, while MYCN-TT + MOXD1 KO–derived tumors largely consisted of cancer cells." (PMID 38905335, 2024). "Because high H2AFY mRNA expression is associated with a more proliferative cancer phenotype, we tested its prognostic value independent of MYCN amplification." (PMID 39255035, 2024). "Single-cell RNA sequencing of human clinical HGSC samples revealed a strong negative association between cancer cell–intrinsic MYCN transcriptional program and type I IFN signaling." (PMID 38748789, 2024). "Due to the versatility of MYCN, the key activities and mechanisms by which MYCN drives cancer remain unclear." (PMID 39334719, 2024). "MYCN significantly enhances protein synthesis, particularly in MYCN‐driven cancers." (PMID 37975412, 2024). "Additionally, the concept of “cysteine addiction” in cancer is linked to the MYCN gene; cysteine depletion triggers extensive lipid peroxidation, suggesting its pivotal role in MYC-driven cancer processes." (PMID 39981299, 2024).
cancer (continued). "This potential dependency on DDX3X for efficient translation could have profound implications for MYCN‐enhanced global protein synthesis and, consequently, the growth of these cancers." (PMID 37975412, 2024). "Under the pressure of oncogenic stimuli such as MYCN aberrant expression, dysregulation of the signaling pathway in neural crest cell may generate highly malignant NB cancer stem cells (CSC) subsets." (PMID 36874032, 2023). "Our model in which MYCN selectively activates canonical MYC targets through binding promoters and represses cell lineage specific differentiation genes through binding enhancers more fully rationalizes the different oncogenic cellular effects driven by MYCN in different types of cancer cells." (PMID 37781575, 2023). "Through genomic amplification, chromosomal translocation or mutagenesis in the signaling pathways, MYCN expression may abnormally rise leading to elevated N-Myc levels in human cancers particularly in neuroblastoma." (PMID 37884585, 2023). "CD532, an AURKA kinase-independent confirmation-specific inhibitor, disrupts the AURKA-MYCN complex and drives the proteasomal degradation of MYCN in MYCN-driven cancers, suggesting a strategy to overcome AURKA kinase-independent oncogenic activity by disrupting protein-protein interactions." (PMID 37415951, 2023). "In addition, studies have shown that the inhibitors of CDK7(THZ1) or CDK9(CYC065) can disrupt abnormal MYCN-driven transcription and inhibit MYCN gene transcription, becoming potential anti-cancer drugs." (PMID 36770809, 2023). "However, inhibition of MYCN protein binding partners (MYCN-BPs) is emerging as an efficient strategy for targeting MYCN oncogenic signalling in the treatment of MYCN-driven cancers." (PMID 36980710, 2023). "MYCN forms a dynamic complex system with different cofactors on different genomic loci to control the chromatin landscape, guide the expression of genes, and determine the malignant cancer cell identity." (PMID 37781575, 2023). "Thus, our data offer another example of a precision medicine approach, in which different tumors are unified in their targeted therapy treatment by their common driver cancer gene (MYCN)." (PMID 36765949, 2023). "Moreover, the reduction in mRNA levels of MYCN and stemness-related transcription factors in cancer stem-like cells that was impaired by upregulated ADAMTS9-AS2 expression was rescued by overexpressing LIN28B." (PMID 37991019, 2023). "As with other cancers, a MYCN gain serves as a poor prognostic indicator in both settings." (PMID 37239954, 2023). "Therefore, block of MYCN is thought to be a therapeutic approach in MYCN-driven cancers but the development of pharmacological inhibitors directly targeting MYCN proteins has been challenging." (PMID 37543638, 2023). "Deregulated expression of the MYC family of oncogenes/transcription factors MYC, MYCN, and MYCL (here collectively referred to as “MYC”) occurs in more than half of all cancers, and is often strongly associated with aggressive tumors, resistance to therapy, and poor prognosis." (PMID 36874405, 2022). "Unconstrained growth in MYC- and MYCN-driven cancers is thus dependent on metabolic pathways, which may serve as novel targets for cancer therapy." (PMID 35943801, 2022). "The cysteine requirement of cancers dependent on oncogenic MYCN activity creates a previously unknown Achilles’ heel that could be exploited to selectively induce ferroptosis for treatment." (PMID 35484422, 2022). "Further studies revealed that SMAD9 bound to the MYCN promoter and transcriptionally regulate MYCN expression, with MYCN reciprocally binding to the SMAD9 enhancer and transactivating SMAD9, thus forming a positive feedback loop along with the MYCN-associated cancer cell cycle." (PMID 36539767, 2022).
cancer (continued). "On the other hand, in transcriptional misregulation in the cancer signaling pathway, only MYCN expression was notably decreased, and the expression of 20 genes, including GADD45A, CXCL8, JMJD1C, RUNX1, and H3C14, was significantly increased in NHEKs upon HPV8 E7 expression." (PMID 35665406, 2022). "The mechanism of enhancer hijacking is used by NB cancer cells to activate c-MYC/MYCN expression." (PMID 35277192, 2022). "The combined analysis of SMAD9 binding patterns and transcriptomic changes in SMAD9 knockdown cells indicated that SMAD9 might contribute to MYCN-mediated autonomous tumorigenicity and the cancer cell cycle in MYCN-amplified NB." (PMID 36539767, 2022). "Furthermore, by targeting MYCN, a cancer-specific mTOR pathway inhibition occurs only in MNA-NB, thus avoiding the side effects of targeting mTOR in normal cells." (PMID 35490242, 2022). "We conclude that MYCN over-expression is sufficient to drive tumorigenesis and that a cell-specific resistance to apoptosis in the cone/horizontal cell lineage mediates the cancer phenotype." (PMID 35729105, 2022). "Amplification of the MYCN oncogene in this cancer is detected in 20–30% of cases and is associated with non-effective chemotherapy." (PMID 36793345, 2022). "Therefore, developing novel single-agent therapeutic strategies targeting multiple oncogenic pathways such as PI3K/AKT, histone deacetylases, and MYCN, is important for NB and other cancers." (PMID 35205815, 2022). "Our initial findings with the anti-NB efficacy of MYCN/mTOR inhibition on neurospheres and stem cell markers indicate that individual or combined inhibition of MYCN/mTOR might target cancer stem cells - potentially minimizing recurrence of NB." (PMID 34565342, 2021). "Our data indicate that MYCN is overexpressed in RB, and that may contribute to the disease progression by altering the cancer metabolism (glucose metabolism) and cell migration related genes." (PMID 34680394, 2021). "Together, our findings indicate that EGFR plays an important role in the regulatory network and pathways of MYCN and therefore may represent an attractive therapeutic target for cancer treatment." (PMID 33968733, 2021). "Some hints suggest that MYCN overexpression leads to cancer immune-escape." (PMID 33718189, 2021). "We hypothesised that ALK-driven NB, which often involves MYCN amplification, may also represent a situation where cancer cells are more dependent on the integrity of ATR-regulated checkpoint responses and therefore sensitive to ATR inhibitors." (PMID 34819497, 2021). "N-Myc expression is elevated due to amplification of the MYCN gene in many cancers." (PMID 33397405, 2021). "Since inhibitors of BET proteins, including OTX and structurally similar inhibitors to JQ1, are currently in clinical trials for several cancers, it is more likely that combination of TEM with BET inhibitors can be translated in clinic for NB and other MYC/MYCN-driven cancers therapies." (PMID 34565342, 2021). "We used cis-X to focus here on MYCN, a cancer-associated gene significant by SVExpress but not SV-HotSpot." (PMID 33743584, 2021). "This is almost reminiscent of the prognostic value of MYCN itself for this type of cancer." (PMID 34423893, 2021). "These include well-known cancer-associated genes, such as CCND1 (25 tumors), CDK4 (25 tumors), MDM2 (23 tumors), SETDB1 (23 tumors), ERBB3 (11 tumors), ERBB2 (11 tumors), MYC (10 tumors) and MYCN (five tumors)." (PMID 32025003, 2020). "Whether the cancer-promoting effect mediated by HOXD-AS1 can be reversed by MYCN, we also perform rescue experiments." (PMID 32857725, 2020). "These upregulated target genes are enriched for the pathways involved in metabolism (e.g., SLC3A2, SLC7A5) and mitochondrial gene expression (e.g., PNPT1), consistent with previous studies, demonstrating that elevated MYC/MYCN induces metabolic reprogramming in cancer cells." (PMID 32060267, 2020).
cancer (continued). "Given that inhibition of BET by small molecule JQ1 resulted in suppressing MYC expression and thereby induce cell death, a pediatric cancer trial is currently underway including assessing the BET inhibitor BMS-986158 in MB with MYC/MYCN amplification (NCT03936465)." (PMID 32164294, 2020). "Deregulation of MYCN occurs in both pediatric cancers and adult cancers." (PMID 33628735, 2020). "MYCN has been shown to play an apoptotic role in cancer cells under certain circumstances." (PMID 33628735, 2020). "Aberrant expression of MYCN contributes to the tumorigenesis of several cancers." (PMID 32857725, 2020). "In co-amplification with MYCN, MYCNOS may uniquely function only in MYCN-amplified tumors for cancer progression." (PMID 33270844, 2020). "The different response of the two cancer cell populations could be related to the different MYCN status." (PMID 32973970, 2020). "It will be interesting to evaluate whether either of these approaches affects MAX/MYCN interactions to inhibit the growth of MYCN-driven cancers." (PMID 33628735, 2020). "This suggests that increased MYCN expression is an early event in these cancers leading to a peculiar dysregulation of cells that results in embryonal or cancer stem-like qualities, such as increased self-renewal, apoptotic resistance, and metabolic flexibility." (PMID 33585251, 2020). "At another dimension which might be of importance for treatment resistance in MYCN-driven cancer, involves OCT4 phosphorylation at S111 via MAPKAP2 that can promote MYC expression." (PMID 33585252, 2020). "Data mining using the Cancer Cell Line Encyclopedia (CCLE) database identified a total of 65 MYCN mutations, but none of them was detected in HCC cell lines irrespective of their corresponding mRNA abundance." (PMID 33937011, 2020). "Considering that MYCN is amplified in many pediatric cancer entities that differ in chromatin landscape, we hypothesized that MYCN amplicon structure should also differ between cancer entities." (PMID 33199677, 2020). "MYCN amplification is a prototypical example of a cancer-driving amplification." (PMID 33199677, 2020). "Thus, targeting MYCN at branch points involved in its oncogenic regulation of transcription is an important therapeutic approach for MYCN-driven cancers." (PMID 33628735, 2020). "MYCN regulates diverse cellular processes during development and in cancer." (PMID 32060267, 2020). "As expected, cancer-promoting function on proliferation, invasion, stemness maintenance and chemo-resistance generated by miR-520c-3p knockdown was retrieved in part through silencing MYCN." (PMID 32857725, 2020). "AKT2, BCL2, EWSR1 retrogene and MYCN for their cancer notoriety)." (PMID 30890123, 2019). "Moreover, MYCN has been shown to stimulate mitochondrial biogenesis of β-oxidation and glucose metabolism in cancer progression." (PMID 31624245, 2019). "Since MYCN is an important oncogene and its amplification is observed in many cancers, the role of chromatin remodeling for MYCN may be conserved in other cancers." (PMID 31396265, 2019). "MYCNOS-01 affects cell growth of MYCN-amplified RMS and NB and could also play a role in other MYCN-driven cancers." (PMID 29466962, 2018). "Whether the MRN complex is essential to prevent the deleterious effects of MYCN-dependent RS also in cancer cells was poorly investigated, so far." (PMID 30166519, 2018). "Future immunotoxins based on this enzyme may therefore have higher specificity towards MYCN-amplified cancer cells than more conventional ribosome-inactivating proteins, leading to an increased therapeutic window and decreased side effects." (PMID 29954071, 2018). "Due to its essential role in limiting the deleterious effect of RS in MYCN-driven cancer cells, MRE11 might represent a novel therapeutic target for MYCN-driven tumors." (PMID 30166519, 2018). "Another regulator of apoptosis, H-TWIST, is often overexpressed in MYCN-amplified cancers." (PMID 28358317, 2017).
cancer (continued). "Importantly, there is a great potential to integrate the inhibition of MYCN function to strategies for novel cancer treatments." (PMID 28358317, 2017). "Furthermore, MYCN-promoted SGO1 transcription and SGO1 expression tended to be higher in MYCN- or MYC-overexpressing cancers." (PMID 27539729, 2016). "Based on these findings, PET imaging may be further studied as a biomarker that identifies patients with NB or other cancers who would most likely to benefit from novel therapies targeting MYC/MYCN or the glycolytic pathway." (PMID 26959748, 2016). "Importantly, CD532 inhibits Aurora-A at low nanomolar concentrations and, in parallel, effects the proteolytic degradation of MYCN proposing an additional strategy to block MYCN in cancer." (PMID 26734566, 2015). ", suggesting that MYCN acts to expand a cancer propagating cell within neurosphere cultures." (PMID 25785590, 2015). "PRMT5 inhibition may therefore represent a novel alternative for treatment of NB and other cancers driven by the MYCN oncoprotein." (PMID 25475372, 2015). "Regardless of the mechanism, these results clearly suggest that targeting MYCN with a single drug may only result in the short-term remission, and thus a combinatorial treatment with other drugs may be necessarily to eradicate cancer cells." (PMID 25785590, 2015). "The MYC family of proto-oncogenes (MYC, MYCN, and MYCL) has been broadly implicated in cancer." (PMID 26029667, 2015). "It thus was hypothesized that interfering with MYCN functions will offer a route to tackle the most aggressive forms on NB and other MYCN-dependent cancers." (PMID 26029996, 2015). "Furthermore, we and others have shown that inhibiting the MYCN associate EZH2 or other enzymes that modify the chromatin landscape causes reactivation of CLU and other potential tumor suppressor genes in cancer cells with therapeutic effects (16, –, 18)." (PMID 25477524, 2015). "MYCN is a transcription factor that plays key roles in both normal development and cancer." (PMID 25294817, 2015). "Further investigation of the regulatory role of AHR in the expression of MYCN may shed light, not only on the pathogenesis of NB, but also on a novel prevention or treatment for this devastating cancer." (PMID 24586395, 2014). "While many groups are looking for strategies aimed at directly targeting Myc, recent discoveries opened the possibility to deliver target therapies for MNA tumors based on synthetic lethal approaches or by enhancing the anti-cancer pathways intrinsically activated by MYCN." (PMID 23091802, 2012). "In addition to its role in tumorigenesis, MYCN sensitizes untransformed and cancer cells to apoptosis." (PMID 23091802, 2012). "In these regions, five known cancer related genes are included, one of which is MYCN." (PMID 21569311, 2011). "After activation of MYCN, western blot analysis showed that B-MYB is induced at the protein level, validating the hypothesis that B-MYB is under the control of MYCN in human cancer cell lines." (PMID 21304178, 2010). "We conclude that MYCN and B-MYB are engaged in a reciprocal regulatory loop whose pharmacological targeting could be beneficial to patients with the aggressive forms of cancer in which MYCN is amplified." (PMID 21304178, 2010). "We thus propose that down-regulation of MYCN in Daoy cancer cells after Msi1 depletion might induce expression of the Wnt repressor DKK1, therefore interconnecting Msi1, Wnt and Hedgehog signaling pathways." (PMID 18826648, 2008).